U2 (U2 spliceosomal RNA )
Synonyms: LOC124902096
Gene: Small nuclear RNA gene on chromosome 8 (109,873,913 to 109,874,018, reverse strand). Ensembl gene ENSG00000283555.
Gene Ontology:
Molecular function: pre-mRNA branch point binding
Biological process: mRNA branch site recognition
Cellular component: U2 snRNP
Homologues: Orthologues: macaque U2 (98% identical), rabbit U2 (64% identical), rabbit U2 (58% identical). Paralogues in human: RNU2-36P (66% identical), RNU2-2 (65% identical), RNU2-32P (65% identical), RNU2-59P (65% identical), U2 (65% identical), RNU2-17P (64% identical), RNU2-4P (64% identical), RNU2-6P (64% identical), RNU2-26P (63% identical), RNU2-3P (63% identical), RNU2-47P (63% identical), RNU2-5P (63% identical), and 66 more.